RASAL3 (RAS protein activator like 3)
Description:
Functions as a Ras GTPase-activating protein. Plays an important role in the expansion and functions of natural killer T (NKT) cells in the liver by negatively regulating RAS activity and the down-stream ERK signaling pathway.
Synonyms: FLJ21438
Tractability: PROTAC: ubiquitination databases record sites on it; its protein half-life has been measured.
Gene: Protein-coding gene on chromosome 19 (15,451,624 to 15,464,583, reverse strand). Ensembl gene ENSG00000105122.
Subcellular location: Cytoplasm; Cytoplasm, cell cortex
Subcellular location (Human Protein Atlas): Nucleoplasm; Plasma membrane
Pathways (Reactome):
Signal Transduction: Regulation of RAS by GAPs
Gene Ontology:
Molecular function: identical protein binding; protein binding; GTPase activator activity
Biological process: negative regulation of Ras protein signal transduction; positive regulation of NK T cell proliferation; regulation of intracellular signal transduction
Cellular component: cytoplasm; cytoplasmic side of membrane; extracellular exosome; membrane; plasma membrane; cytosol; cell cortex
Genetic constraint (gnomAD): Loss-of-function variants: 74 observed, 87.08 expected, observed/expected ratio (o/e) 0.85, 90% interval 0.7 to 1.03. The synonymous counts are far from expectation, so gnomAD's model fits this gene poorly and the ratio says little. Missense variants: 1,352 observed, 1,207.1 expected, observed/expected ratio (o/e) 1.12, 90% interval 1.07 to 1.17. Synonymous variants: 579 observed, 490.31 expected, observed/expected ratio (o/e) 1.18, 90% interval 1.1 to 1.26.
Homologues: Orthologues: chimpanzee RASAL3 (99% identical), macaque RASAL3 (97% identical), dog RASAL3 (85% identical), pig RASAL3 (84% identical), guinea pig RASAL3 (81% identical), mouse Rasal3 (81% identical), rat Rasal3 (80% identical), tropical clawed frog rasal3 (38% identical), zebrafish rasal3 (37% identical), Caenorhabditis elegans gap-2 (24% identical), Drosophila melanogaster raskol (15% identical), Drosophila melanogaster RasGAP1 (12% identical), and 1 more. Paralogues in human: DAB2IP (33% identical), RASAL2 (32% identical), RASAL1 (14% identical), NF1 (14% identical), RASA4 (14% identical), RASA4B (14% identical), RASA3 (14% identical), RASA1 (13% identical), RASA2 (12% identical).
Diseases named in the same sentence as RASAL3 in open-access papers:
RASAL3 is named in the same sentence as 21 diseases in open-access papers, as found by Europe PMC text mining. Sharing a sentence is not in itself a finding about the gene and the disease. The quoted sentences say what the papers report.
prostate carcinoma (4 papers, 2019 to 2024). A carcinoma that arises from epithelial cells of the prostate gland. "Much less studied, RASAL3 epigenetic silencing in fibroblasts was linked to reprogramming of the tumor stroma in prostate cancer patients failing androgen deprivation therapy." (PMID 33096593, 2020). "Hypermethylation of RASAL3 on exon 2 was observed in prostate cancer associated fibroblasts (CAFs), favoring Ras signaling and metabolic reprograming in CAFs and cancer cells, fostering their proliferation." (PMID 33096593, 2020). "For prostate cancer, promoter hypermethylation and silencing of the RasGAP, RASAL3 that resulted in the activation of Ras signaling in carcinoma-associated fibroblasts." (PMID 31627186, 2019).
acute myeloid leukemia (2 papers, 2024 to 2025). Acute myeloid leukemia (AML) is a group of neoplasms arising from precursor cells committed to the myeloid cell-line differentiation. "Besides, in acute myeloid leukemia (AML), TREM2, as a novel receptor for IL-34, can induce myeloid differentiation and inhibit AML progression by inhibiting the ERK1/2/Rasal3 signaling pathway." (PMID 38725629, 2024).
colorectal cancer (2 papers, 2024). A primary or metastatic malignant neoplasm that affects the colon or rectum. "Also, the Rasal3 mutation causes a unique susceptibility to colitis-associated colorectal cancer phenotype not seen in the Ccdc88b or Arhgef2 mutants." (PMID 38200184, 2024).
diverticulitis (2 papers, 2020 to 2024). An infection that develops in the diverticula of the intestinal tract. "Hub genes RASAL3, SASH3, PTPRC, and INPP5D were found to upregulate immune response-associated transcripts in the sigmoid colons of chronic, recurrent diverticulitis patients as identified by Schiefer et al25." (PMID 38831715, 2024). "They further identified four immune-regulatory hub genes: RAS protein activator-like 3 (RASAL3), protein tyrosine phosphatase, receptor type C (PTPRC), inositol polyphosphate-5-phophatase D (INPP5D), and SAM and SH3 domain-containing 3 (SASH3) that were associated with diverticulitis." (PMID 32635383, 2020). "This built on earlier work, by the same team, which suggested the hub genes RASAL3, SASH3, PTPRC and INPP5D within the brown module eigengene were highly correlated (r = 0.67, P = 0.0004) with diverticulitis." (PMID 38831715, 2024).
Sepsis (2 papers, 2021 to 2024). Sepsis is defined as life-threatening organ dysfunction caused by a dysregulated host response to infection. "We hypothesized that RASAL3 deficiency in neutrophils may contribute to sepsis pathogenesis." (PMID 34777356, 2021). "The identification and use of RASAL3 agonists, which are yet to be identified at the time of this report, may serve as a novel therapeutic target in sepsis and other neutrophil-driven inflammatory conditions." (PMID 34777356, 2021).
colitis (1 paper, 2024). Inflammation of the colon. "Mice defective in Arhgef2 or Rasal3 show dampened neuroinflammation, and display altered cellular response and susceptibility to colitis; ARHGEF2 maps to a human Chromosome 1 locus associated with susceptibility to IBD." (PMID 38200184, 2024). "To better understand the susceptibility of Arhgef2−/− and Rasal3−/− mice to colitis, we conducted cellular immunophenotyping of colon cell populations by flow cytometry following DSS treatment." (PMID 38200184, 2024). "CCDC88B physically interacts with ARHGEF2 and RASAL3; defective mice show dampened neuroinflammation, altered susceptibility to colitis and altered DCs motility by modulating RHOA, with ARHGEF2 and RASAL3 acting in opposite regulatory fashions." (PMID 38200184, 2024). "Interestingly, loss of Rasal3 or Arhgef2 also exacerbates the effect of DSS induced colitis." (PMID 38200184, 2024). "This suggests that RASAL3 is require for the proper function of T lymphocytes during colitis, in agreement with recently published studies." (PMID 38200184, 2024). "Taken together, these results indicate an altered response of Rasal3−/− and Arhgef2−/− mice to acute DSS-induced colitis, with higher susceptibility and increased pathology and enhanced inflammatory response." (PMID 38200184, 2024). "We therefore tested the response of Arhgef2−/− and Rasal3−/− mutant to DSS-induced colitis." (PMID 38200184, 2024). "Hence, although mutations in Arhgef2 and Rasal3 have opposite effects on DC migration, they cause similar pathological effects in DSS-colitis, albeit with different leukocytes infiltrates." (PMID 38200184, 2024). "Their functional interaction was established in vivo: Arhgef2−/− and Rasal3−/− mutants display resistance to neuroinflammation in EAE (alike Ccdc88bmut mice), and show altered inflammatory response during DSS induced colitis." (PMID 38200184, 2024). "Conversely, transfer of Rasal3−/− naive T cells failed to induce colitis when compared to B6, exhibiting both a decrease in the amount of infiltrating CD3+ T cells and a lower pathology score." (PMID 38200184, 2024). "To further investigate the contribution of lymphoid cells to the exacerbated colitis phenotype seen in Rasal3−/− and Arhgef2−/− mice, we tested the ability of B6, Rasal3−/− and Arhgef2−/− naïve CD4+ CD25−CD45RBHi T cells to induce colitis upon adaptive transfer into lymphopenic Rag1−/− mice." (PMID 38200184, 2024).
fungal infections (1 paper, 2023). "It was reported that NKT cells contributed to the defense of host against bacterial and fungal infections, which may explain why RASAL3 was more expressed in patients with IE." (PMID 37332019, 2023).
gastric cancer (1 paper, 2021). A primary or metastatic malignant neoplasm involving the stomach. "Furthermore, several genes belonging to the Ras GTPase-activating protein (RasGAP) family, including RASA3 (P = 0.0005), RASA4 (P = 0.003), and RASAL3 (P = 0.0016), were identified with hypermethylated promotors in EBVaGCs compared with that in precursor lesions and other gastric cancers." (PMID 34493320, 2021).
inflammatory bowel disease (1 paper, 2022). A spectrum of small and large bowel inflammatory diseases of unknown etiology. "These included elevated methylation levels in CpG islands associated with FZD1 and RUNX3, both of which encode proteins that regulate ovarian folliculogenesis, and also RASAL3, which controls a magnitude of inflammatory responses and has been linked specifically to inflammatory bowel disease." (PMID 34996447, 2022).
lung adenocarcinoma (1 paper, 2022). A carcinoma that arises from the lung and is characterized by the presence of malignant glandular epithelial cells. "RAS‐activating protein‐like 3 (RASAL3) is a synaptic Ras GTPase‐activating protein (SynGAP) and a potential novel biomarker of CD8+ T cell infiltration in lung adenocarcinoma (LUAD)." (PMID 36420686, 2022).
Mycoplasma pneumoniae pneumonia (1 paper, 2021). Interstitial pneumonia caused by extensive infection of the lungs (lung) and bronchi, particularly the lower lobes of the lungs, by mycoplasma pneumoniae in humans. "RASAL3 is significantly upregulated in Mycoplasma pneumoniae pneumonia (MPP) children, and NK cells are involved in the pathogenesis of MPP46." (PMID 34349215, 2021).
sarcoma (1 paper, 2020). A usually aggressive malignant neoplasm of the soft tissue or bone. "Three hub genes (CD48, P2RY10, and RASAL3) associated with immunotherapy and the development of sarcomas were analyzed and presented, as potential prognostic biomarkers and/or therapeutic targets of immunotherapy for sarcomas." (PMID 33292275, 2020). "In addition, immunohistochemistry (IHC) staining data acquired from the HPAD also confirmed the differential expression of the predicted genes (CD48, P2RY10, RASAL3) in sarcoma samples." (PMID 33292275, 2020).
sickle cell disease (1 paper, 2021). Sickle cell anemias are chronic hemolytic diseases that may induce three types of acute accidents: severe anemia, severe bacterial infections, and ischemic vasoocclusive accidents (VOA) caused by sickle-shaped red blood cells obstructing small blood vessels and capillaries. "The excessive neutrophilic hyperinflammation and increased mortality were recapitulated in a mouse model of sickle cell disease, which we found to have low neutrophil RASAL3 expression upon LPS activation." (PMID 34777356, 2021). "We first assessed RASAL3 protein expression in circulating neutrophils and monocytes from Townes mouse model of sickle cell disease." (PMID 34777356, 2021).
thymoma (1 paper, 2015). A neoplasm arising from the epithelial cells of the thymus. "The DP thymoma line DPK was transduced with Rasal3 cDNA, which resulted in 10-fold greater Rasal3 protein expression." (PMID 25793935, 2015).
triple-negative breast carcinoma (1 paper, 2022). An invasive breast carcinoma which is negative for expression of estrogen receptor (ER), progesterone receptor (PR), and human epidermal growth factor receptor 2 (HER2). "For CoCNV, some genes in the PMI network gene set can classify patients into groups with significantly different survival probability by their single gene CNV, such as CTLA4, ORM1, and RASAL3 in triple negative breast cancer." (PMID 35610556, 2022).
tumor (6 papers, 2018 to 2024). "The high RASAL3 expression might increase the infiltration of CD8+ tumour‐associated T lymphocytes in LUAD." (PMID 36420686, 2022). "RASAL3 expression was linked to prognosis and CD8+ tumour‐associated T lymphocyte infiltration in LUAD, indicating its potential as a predictive biomarker and immune‐related therapeutic target for LUAD." (PMID 36420686, 2022). "We are convinced that loss of function of RasGAPs in cells that infiltrate the tumor environment, such as endothelial cells and fibroblasts, can have a dramatic impact on tumor development, as hinted by studies on DAB2IP and RASAL3." (PMID 33096593, 2020). "Furthermore, we used TMA‐based IHC to confirm a positive association between RASAL3 expression level and CD8+ tumour‐associated T lymphocyte infiltration." (PMID 36420686, 2022). "In fact, the current use and observed efficacy of such therapeutics may in part be due to their impact on RASAL3 on non-tumor cells." (PMID 31627186, 2019). "In light of the recognized importance of tumor immunity, there may be further justification for the restoration of RASAL3 expression, potentially through the use of HDAC inhibitors or DNA-demethylating agents." (PMID 31627186, 2019). "When MSP was applied to tumour samples, a significant reduction of HOXD10, FGFR2 (P < 0.05), ITIH5 and RASAL3 (P < 0.001) promoter methylation was observed in DEC-treated mice." (PMID 30533020, 2018). "Unlike the other two RASAL family members, RASAL3 has not been considered a tumor suppressor in the traditional sense, in terms of being silenced in tumor cells." (PMID 31627186, 2019). "We note that as opposed to Arhgef2−/− mice that behaved like controls, Rasal3−/− mice showed a significantly greater susceptibility to CA-CRC; this susceptibility was expressed both by an increase in the total number of tumors per colon, and an increase total tumor surface area." (PMID 38200184, 2024).
cancer (3 papers, 2015 to 2019). A tumor composed of atypical neoplastic, often pleomorphic cells that invade other tissues. "Most of these genes have not been previously reported in SS, and neuroguidin (NGDN), RAS protein activator like 3 (RASAL3), KLHL34 and MUM1L1 have not previously been linked to cancer; only one gene (EP300) has been reported in SS." (PMID 26503545, 2015). "Most of these genes have not been previously reported in SSs, and four genes, neuroguidin (NGDN), RAS protein activator like 3 (RASAL3), KLHL34 and MUM1L1, have not been previously linked to cancer." (PMID 26503545, 2015).
RASAL3 also shares sentences with these, for which no sentence is quoted: multiple myeloma (2 papers); diffuse large B-cell lymphoma (1); lung carcinoma (1); lymphoma (1).